CDK4 (cyclin dependent kinase 4)
Diseases named in the same sentence as CDK4 in open-access papers (continued):
Sharing a sentence is not in itself a finding about the gene and the disease.
breast cancer (continued). "Abemaciclib, which demonstrates BBB penetration, is being examined for use as an ER+ endocrine resistance metastatic breast cancer treatment to specifically target CDK4/6 and inhibit cell proliferation." (PMID 35505937, 2022). "In the present study, among five participants with advanced breast cancer previously treated with a CDK4/6 inhibitor in the dose-expansion phase, the only participant evaluable for response (25.0%), who had previously received palbociclib, achieved SD." (PMID 36291780, 2022). "Consistently, cyclin D1 levels alone are not correlated with cell-cycle entry in vitro and therapeutic outcomes of CDK4/6 inhibitors in breast cancer patients." (PMID 36207346, 2022). "Currently developed combinatorial therapies have made remarkable progress in the efficacy of CDK4/6 inhibitors for HR+/HER2- metastatic breast cancer therapy." (PMID 35938171, 2022). "The biochemical profile translated to cell-based assays, with CDK4-dependent breast cancer cell lines showing a profound inhibition of pRb under abemaciclib treatment." (PMID 35813283, 2022). "And its function will also change due to the different subtypes in the same tumor, ER status determines the effect of HDAC5 on the vulnerability to CDK4/6 inhibitors in breast cancer." (PMID 35265200, 2022). "Today, the standard therapy for locally advanced or metastatic HR+/HER2- breast cancer is a combination of cyclin-D-dependent kinase 4 and 6 (CDK4/6) inhibitors with endocrine therapy because of better overall and progression-free survival." (PMID 36364432, 2022). "CDK4/6 inhibitors have recently become available for the treatment of metastatic ERα-positive/HER2-negative breast cancers." (PMID 37435447, 2022). "Despite these challenges, single‐agent endocrine therapy or in combination with CDK4/6 inhibitors remains the primary systemic therapy recommended for locally advanced and metastatic breast cancers." (PMID 35671075, 2022). "Selective regulation of cyclin dependent kinase 4 (CDK4) by gold nanoparticle conjugates induced the G1 cell cycle arrest and apoptosis induction in the ER-positive human breast cancer cells lines, MCF-7." (PMID 35163607, 2022). "Several new generation CDK4/6 inhibitors have been developed and approved for breast cancer therapy in combination with endocrine therapeutics." (PMID 35982453, 2022). "CDK6 increases vascular endothelial growth factor A (VEGF-A) and c-Jun, promoting angiogenesis to allow the promotion of breast cancer progression and CDK4/6I resistance." (PMID 36358806, 2022). "Our comparisons between RPE1 and breast cancer cells did reveal some important differences in how these cells respond to CDK4/6 inhibition." (PMID 35037284, 2022). "The typical breast cancer-targeting drugs of CDK4/6 inhibitors include palbociclib, ribociclib, and abemaciclib." (PMID 35402243, 2022). "The point is, CDK4/6 inhibitors start to improve progression free survival significantly when supported by biomodulatory endocrine therapy, for example in breast cancer." (PMID 35814409, 2022). "Although CDK4/6 inhibitors can effectively improve the prognosis of HR+/HER2– breast cancer, there are differences in the sensitivity to CDK4/6 inhibitors among individuals." (PMID 35711853, 2022). "Acquired resistance of cyclin-dependent kinase (CDK) 4/6 inhibitors occurs in almost all hormone receptor (HR)-positive subtype cases, comprising 70% of breast cancers, although CDK4/6 inhibitors combined with endocrine therapy are highly effective." (PMID 35008374, 2022). "ER + breast cancer frequently demonstrates gain of CCND 1 (cyclin D1) and CDK4 and loss of CDKN2A (p16) and CDKN2C (p18)." (PMID 36229710, 2022). "Clinically, CDK4/6 inhibitors are the preferred systemic therapy for the treatment of patients with metastatic ER+ breast cancer who have become resistant to endocrine therapies; including through acquisition of ESR1 mutations." (PMID 35881485, 2022).
breast cancer (continued). "Two retrospective studies from Italy showed that patients with Luminal B breast cancer had a shorter time to progression when treated either with endocrine therapy and a CDK4/6 inhibitor or with first-line endocrine therapy alone." (PMID 36138404, 2022). "The PAM pathway plays an essential role in cell growth, survival, proliferation, angiogenesis, as well as resistance to endocrine therapy and CDK4/6 inhibitors in breast cancer, making it an important treatment target." (PMID 38089455, 2022). "Our data provide the preclinical rationale for a clinical trial expanding the use of CDK4/6i + RT to difficult-to-control RB-intact breast cancers (including TNBC) and nominate RB status as a predictive biomarker of therapeutic efficacy." (PMID 34932500, 2022). "International guidelines for the treatment of metastatic HR+/HER2(−) breast cancer recommend chemotherapy or hormone therapy as the first therapeutic choice for most patients, either as a single agent or in combination with a CDK4/6 inhibitor." (PMID 35986800, 2022). "For the early G1-to-S-phase cell cycle genes, CDK6 and CCNE1 both showed a strong association with TNBC and basal-like breast cancers in all three cohorts, while CDK2, CDK4 and CCND1 expression were high across all patient samples." (PMID 35884422, 2022). "Short-term inhibition of CDK4/6 has also been shown to sensitize ER+ breast cancers to radiation therapy in pre-clinical models, highlighting an additional use for these agents in combination therapy." (PMID 36051751, 2022). "CDK4/6 is a key regulator of the cell cycle, and inhibition of its pathway is slowly becoming a possible therapeutic strategy for this type of breast cancer, with the opportunity to achieve blockade at the intersection of the ER and HER2 dual pathways." (PMID 36727058, 2022). "To date, the CDK4/6 inhibitors have been proved to interfere with the proliferation of breast cancer cells by decreasing pRb phosphorylation and arresting the cell cycle in the G1 phase." (PMID 36254250, 2022). "CDK4 is an important oncogenic factor in breast cancer and CDK6 plays a role in hematopoietic stem cell differentiation." (PMID 36530984, 2022). "PI3K and Cyclin-Dependent-Kinase-4/6 (CDK4/6) inhibitor combinations have namely also been shown to be of benefit in some types of breast cancer." (PMID 35891353, 2022). "In this context, CDK4/6 inhibitors induce senescence and reduce tumour growth in breast cancer patients." (PMID 35184131, 2022). "Palbociclib is the first CDK4/6 selective inhibitor for breast cancer treatment approved by the FDA." (PMID 35463335, 2022). "The CDK4/6 inhibitors that are currently approved for treating breast cancer target the ATP-binding domains of CDKs 4 and 6 and are highly selective against these kinases." (PMID 35248122, 2022). "CDK4/6 inhibitors play an extremely important role in the field of cancer therapy, especially in breast cancer, and the study of their resistance mechanisms and the overview of their resistance status are the focus of attention worldwide." (PMID 36530984, 2022). "For instance, the inhibitors of CDK4/6 have been approved for the treatment of breast cancer, and inhibitors of HSP90 (geldanamycin (GA), radicicol (RD), and its semisynthetic derivatives) were in preclinical research of tumor." (PMID 35586682, 2022). "After this long follow-up the role of a CDK4/6 inhibitor plus hormone therapy as a first-line treatment for patients with metastatic HR-positive, Her2-negative breast cancer is obvious." (PMID 35540707, 2022). "It is known that CDK4/6 inhibitors (as Palpociclib, Abemaciclib) induce senescence and reduce tumor growth in breast cancer patients." (PMID 36497228, 2022). "In vitro studies have shown that ER+ breast cancer cells quickly adapt to CDK4/6 inhibition, which can be prevented by co-treatment with a PI3K inhibitor." (PMID 36140723, 2022).
breast cancer (continued). "Downregulation of CDK4/6 has been shown to promote cell cycle arrest in endocrine resistant breast cancer by inhibiting the activation of DNA syntheses (S) phase of cell division." (PMID 35505937, 2022). "A recent study has suggested that CDK4/6 degraders are promising alternatives to CDK4/6 kinase inhibitors as they suppress the proliferation of palbociclib resistant breast cancer cells." (PMID 35326705, 2022). "Current NCCN Guideline recommendations for metastatic HR+/HER2−, breast cancer include the addition of CDK4/6Is with hormonal therapy (letrozole, fulvestrant) in postmenopausal and for premenopausal patients as a preferred first-line treatment." (PMID 36358806, 2022). "We also have found that CDK4/6 inhibitor prevents breast cancer metastasis by targeting the CDK4/6-DUB3-Snail axis." (PMID 35383144, 2022). "CDK4/6i (palbociclib, ribociclib, abemaciclib) are relatively new cell cycle inhibitors that have been found to be effective in breast cancer treatment, and are currently being developed in other solid tumors." (PMID 36185294, 2022). "The arrival of FDA-approved anti-CDK4/6 inhibitors (palbociclib and ribociclib) for breast cancer metastasis has made it targeting cell cycle dysregulation more accessible." (PMID 36139498, 2022). "Based on these rationales, the current study investigated the potential synergism of combined eribulin and CDK4/6 inhibitor in a palbociclib-resistant breast cancer setting." (PMID 35008374, 2022). "Currently, three CDK4/6 inhibitors are approved and available to treat breast cancer: palbociclib, ribociclib, and abemaciclib." (PMID 35248122, 2022). "Palbociclib (a CDK4/6 inhibitor) exerts antiproliferative effects on breast cancer cells and induces senescence and cell cycle arrest." (PMID 36072578, 2022). "This approach revealed signals reflective of distinct tissues and cancer types, potentially expanding the toolbox for biomarker discovery in the context of CDK4/6 inhibitors for breast cancer patients." (PMID 36176758, 2022). "Although CDK4/6 inhibitors have revolutionized treatment for breast cancer, and promising antitumor effects of various inhibitors have also been witnessed in clinical or preclinical trials, resistance to CDK4/6 inhibitors is emerging." (PMID 35327487, 2022). "In the past decades, a great amount of effort has been directed toward developing inhibitors of CDK, resulting in the success of CDK4/6 inhibitors (palbociclib, ribociclib, and abemaciclib) for the treatment of advanced breast cancer." (PMID 35383271, 2022). "In this review, we discuss biomarker-directed treatment for breast cancer, mechanisms of resistance to CDK4/6 inhibitors, and attempts to uncover ctDNA liquid biopsy biomarkers of efficacy and resistance to CDK4/6 inhibitors." (PMID 36176758, 2022). "HR+/HER2(−) breast cancer patients in urban mainland China were prescribed chemotherapy regimens more frequently than CDK4/6 inhibitors." (PMID 35986800, 2022). "All nine patients with HR+ breast cancer had received prior therapy with a CDK4/6 inhibitor: four in the dose-escalation phase and five in the dose-expansion phase." (PMID 36291780, 2022). "A pooled ctDNA analysis was performed, which combined results of 1503 patients from the MONALEESA-2, -5, and -7 trials to identify biomarkers for CDK4/6 inhibition in the advanced breast cancer." (PMID 35887191, 2022). "As cells enter the G1 phase, CDK4/6 complexes phosphorylate TFEB, leading to its nuclear export and inactivation, and CDK4/6 inhibition increases lysosome biogenesis in breast cancer cells." (PMID 35216401, 2022). "CDK4/6I phosphorylate AKT via PDK1 to activate PI3K/AKT/mTOR pathways in ribociclib-resistant breast cancer cells." (PMID 36358806, 2022). "In preclinical studies using breast cancer cell lines, an intact RB axis was required for sensitivity to CDK4/6 inhibitors." (PMID 36051751, 2022).
breast cancer (continued). "Upregulation of CDK4/6 expression is believed to promote breast cancer tumor cell proliferation in endocrine resistant tumors." (PMID 35505937, 2022). "Altogether, these data show the potential of using F9 levels as a biomarker for patient stratification not only to predict response to CDK4/6 inhibitors but also as a prognostic marker to determine overall survival in breast cancer." (PMID 35184131, 2022). "Based on these results, we propose mTOR inhibitors in combination with CDK4/6 inhibitors as a potential therapeutic strategy in ER+HER2− breast cancers with S6K1 amplification." (PMID 36042494, 2022). "The activation of cyclin D and CDK4/6, which play pivotal roles in the transition from G1 to S phase, is a feature of many cancer cell types, particularly breast cancer cells, and so both have been targeted therapeutically." (PMID 35674109, 2022). "It realized the visualization of CDK4 activity in living cells and in vivo, and initially assessed the therapeutic efficacy of CDK4 inhibitors in the treatment of HR+/HER2‐ breast cancer in pre‐clinical experiments." (PMID 35711853, 2022). "For breast cancer, the commonly used first-line treatment is a combination of CDK4/6 inhibitors, such as palbociclib, with endocrine drugs." (PMID 35931744, 2022). "Palbociclib is the first-in-class CDK4/6 inhibitor approved for the treatment of patients with ER+/HER2- advanced breast cancer." (PMID 35740538, 2022). "For example, CDK4/6 inhibitors have been developed and approved for the treatment of advanced or metastatic ER+/HER2− breast cancer due to the essential role of CDK4/6 in cell cycle regulation." (PMID 35449080, 2022). "Advances in the treatment of HR+/HER2- breast cancer phenotype have been made with the introduction of abemaciclib, ribociclib, and palbociclib, inhibitors of cyclin D dependent kinases 4 and 6 (CDK4/6)." (PMID 36364432, 2022). "His earliest article on this area was a review published in 2014 in Current Opinion in Oncology, Cyclin-dependent kinase 4/6 inhibitors in breast cancer therapy, with an impact factor of 3.915 and 27 citations to date." (PMID 36530984, 2022). "There are attempts to combine CDK4/6 inhibitors with MEK inhibitors (for RAS-driven cancers) or PI3K inhibitors (for breast cancer), but to our knowledge this study is the first to propose the use of E2F/STAT3 inhibitor combination for GBM treatment." (PMID 35058574, 2022). "In breast cancer, the most extensively studied kinases are CDK4 and CDK6, their interaction with cyclin D can result in cell cycle transition from the G0 to G1 phase." (PMID 35205737, 2022). "In this case, the adverse effects of abemaciclib, a cyclin-dependent kinase 4/6 inhibitor playing an essential role in breast cancer treatment, were discovered by combining blood, imaging, and bronchoalveolar lavage fluid findings." (PMID 35251813, 2022). "Hippo signaling in ER+ breast cancer is an established tumor suppressor in ER+ MBC, and FAT1 loss serves as a mechanism of resistance to CDK4/6i." (PMID 35804935, 2022). "More specifically, we have analyzed patients with prostate cancer under treatment with an androgen receptor targeted agent, ovarian cancer receiving treatment with PARP inhibitors and breast cancer patients under treatment with CDK4/6 inhibitors." (PMID 36146552, 2022). "Patients with breast cancer who underwent the treatment of CDK4/6 inhibitors developed SARS-CoV-2 NAbs in response to the first dose of COVID-19 vaccines, similar to the general population." (PMID 35992886, 2022). "Clinical trials demonstrate that CDK4/6 inhibitors prolong the progression-free survival in patients with estrogen receptor (ER)-positive breast cancer when combined with anti-estrogen therapy." (PMID 36145516, 2022).
breast cancer (continued). "The modest monoactivity of CDK4/6 inhibitors or elotuzumab in comparison to edited tumor tissue - with antihormonal therapy approaches in breast cancer and lenalidomide plus dexamethasone in multiple myeloma, respectively, - are pivotal examples." (PMID 35814409, 2022). "Despite improved clinical outcomes in advanced/metastatic HR+/HER2– breast cancer, the utility of CDK4/6 inhibitors is limited by intrinsic resistance (in approximately 10% of patients) and the acquired resistance that inevitably emerges over time." (PMID 36291780, 2022). "Pharmacologically targeting cyclin-dependent kinase 4 and 6 (CDK4 & 6) has proven to be a successful therapeutic approach in patients with estrogen receptor-positive (ER+) breast cancer." (PMID 35813283, 2022). "Inhibition of CDK4/6 promotes the activation of AKT signalling in breast cancer cells, which results in cyclin D1 accumulation." (PMID 36042494, 2022). "Palbociclib, Ribociclib, and Abemaciclib are CDK4/6 inhibitors approved by the FDA for the treatment of breast cancer, but patients develop drug resistance with long-term use." (PMID 36744210, 2022). "Loss of INK4 and Cip/Kip family (inhibitors of CDK4/6) and overexpression of CDK4/6 have also been noted in breast cancer." (PMID 35736347, 2022). "MDA-MB-453 LAR-type breast cancer cells are highly sensitive to CDK4/6 inhibitors, and enzalutamide enhances the efficacy of palbociclib in AR-positive/RB-proficient TNBC cells." (PMID 37435447, 2022). "Provided that the combination therapy is well tolerated, these data will also inform the planned phase II randomized clinical trial evaluating the efficacy of combined CDK4/6i and RT in women with multiple lymph node–positive (LN+) ER+ breast cancer (>3 LN)." (PMID 34932500, 2022). "In breast cancer, the CDK4/6 inhibitor Palbociclib, has already been successfully used for the treatment of oestrogen receptor-positive metastatic breast cancer and other breast cancer subtypes." (PMID 35891353, 2022). "Further studies are needed to confirm our findings and explore the potential crosstalk between CCNE1 and other genes in cell cycle regulation during resistance to CDK4/6 inhibitors in ER+ breast cancer." (PMID 35740538, 2022). "The utility of CDK4/6 inhibitors as monotherapy or in combination with other targeted therapeutics is being explored in breast cancer and other tumor types." (PMID 36051751, 2022). "Three structurally distinct CDK4/6 inhibitors have recently been licenced for breast cancer treatment: palbociclib, ribociclib and abemaciclib (Knudsen & Witkiewicz, 2017; Alvarez‐Fernandez & Malumbres, 2020)." (PMID 35037284, 2022). "CDK4 is a protein of G1/S phase transition in the cell cycle, and CDK4/6 inhibitors have been applied to breast cancer therapy." (PMID 36292719, 2022). "Currently, three CDK4/6 inhibitors have been approved in combination with hormonal therapies for the treatment of breast cancer patients, but patients are prone to develop drug resistance with long-term use." (PMID 36744210, 2022). "In general, cyclin D is overexpressed in breast cancer cells, but it requires CDK4 to perform its function, namely, as a cell cycle regulator." (PMID 36106139, 2022). "Treatment with PI3K or CDK4/6 inhibitors have also been shown to remodel the chromatin landscape of breast cancer, specifically at enhancers." (PMID 35774123, 2022). "A growing body of evidence has shown significantly prolonged progression-free survival and a manageable toxicity profile for first-line CDK4/6 inhibitor plus AI in patients with hormone receptor-positive/HER2-negative advanced breast cancer." (PMID 35397518, 2022).